CXCL5 (C-X-C motif chemokine ligand 5)
Diseases named in the same sentence as CXCL5 in open-access papers (continued):
Sharing a sentence is not in itself a finding about the gene and the disease.
metastatic disease (3 papers, 2019 to 2024). "The unexpected therapeutic effects of CXCR2 CAR-T in the PDAC liver metastasis model may be due to the more exposed recognition of CXCL5 in metastatic tumors compared to the shielding of the stroma structure in primary tumors." (PMID 38430267, 2024). "CXCL5/CXCR2 pathway facilitates the development of metastatic disease in other cancers." (PMID 36968223, 2023). "Future in vivo validation of CXCL5 actions on breast cancer cells at metastatic bone niches in breast cancer patients with metastatic disease will further support our ex vivo culture findings that led to the identification of CXCL5 as a mechanism of bone colonization." (PMID 31562303, 2019). "Therefore, the CXCL5/CXCR2 axis may be physiologically relevant to human patients affected by metastatic disease to the bones from breast cancer." (PMID 31562303, 2019).
pancreatic adenocarcinoma (3 papers, 2020 to 2025). "Next, we investigated the impact of Cxcl5-dependent genes on the survival of pancreatic adenocarcinoma (PAAD) patients." (PMID 40050422, 2025).
pneumococcal pneumonia (3 papers, 2019 to 2025). A febrile disease caused by STREPTOCOCCUS PNEUMONIAE. "A key role of Cxcl5 had been shown in lung inflammation such as that occurred in the mouse model of pneumococcal pneumonia." (PMID 30634975, 2019). "The expression of Cxcl5 accompanying pneumococcal pneumonia had been shown to be induced by NF-κB activation." (PMID 30634975, 2019). "However, in response to pneumococcal pneumonia, ATI cells have been shown to produce CXCL5 (C-X-C motif chemokine ligand 5) in a RelA-independent manner." (PMID 36829255, 2023).
sarcopenia (3 papers, 2019 to 2023). Progressive decline in muscle mass due to aging which results in decreased functional capacity of muscles. "Increased levels of IL-1α, IL17A and CXCL5 have been linked to sarcopenia and cardiotoxicity." (PMID 36611902, 2022). "To date, no research has been conducted to determine if there are relationships between CXCL5 and H3Cit to skeletal muscle breakdown and sarcopenia." (PMID 37906352, 2023). "Relationships between CXCL5 and H3Cit to sarcopenia, anthropometric indices and cachexia are unexplored, with this study pioneering an attempt to find relationships in this regard." (PMID 37906352, 2023).
Streptococcus pneumoniae infection (3 papers, 2018 to 2024). "In our approach, using outbred mouse stocks, only reduced secretion of CXCL5, a chemokine previously shown to be produced by EC during pneumococcal infection, could be related with the increased susceptibility of AIRmin mice to pneumococcal infection." (PMID 29119707, 2018). "Our results support that differences in inflammatory responses can influence the outcome of pneumococcal infection and indicate that impaired expression of CXCL‐5 and matrix metalloproteinases is associated with susceptibility to invasive infection with a serotype 3 pneumococcal strain." (PMID 29119707, 2018). "In a previous study we observed lower numbers of infiltrated neutrophils and lower concentrations of the CXCL5 chemokine in BALFs of AIRmin mice, at 12 h after pneumococcal infection, when compared to AIRmax mice." (PMID 39641265, 2024). "Induction of high levels of CXCL5 was observed in AIRmax mice at 12 h after pneumococcal infection and the levels of this chemokine reduced at 48 h post‐infection, in association with the reduction in bacterial burden." (PMID 29119707, 2018). "CXCL5 was the only chemokine that showed a diverse pattern of expression in AIRmin and AIRmax responses to pneumococcal infection." (PMID 29119707, 2018). "Our results indicate that CXCL5 and MMPs contribute to the resistance to pneumococcal infection in mice." (PMID 29119707, 2018). "Yamamoto and collaborators have previously shown that CXCL5 is expressed by lung epithelial cells (EC) in response to pneumococcal infection." (PMID 29119707, 2018). "Here we confirmed that AIRmax mice have higher numbers of circulating neutrophils and also observed higher concentrations of the neutrophil chemoattractant CXCL5 in the blood, which may contribute for its natural resistance to pneumococcal infection." (PMID 39641265, 2024). "The only exception was CXCL5, which was highly induced after pneumococcal infection in AIRmax mice but not in AIRmin mice." (PMID 29119707, 2018). "Whereas pneumococcal infection induced the secretion of high levels of CXCL5 in the airways of AIRmax mice, no response was observed in AIRmin mice." (PMID 29119707, 2018).
trachoma (3 papers, 2014 to 2016). "MMP7, CXCL5 and IL-17A were strongly associated with inflammatory episodes but not with progressive scarring in two large cohorts of individuals with trachoma." (PMID 27249027, 2016). "IL-17A, CXCL5, PDGF, MMP7 and MMP9 have previously been associated with various stages of trachoma (trachomatous inflammation–follicular, TS and TT) at mRNA and protein expression levels, however they were not demonstrably up-regulated in TT cases in the present study." (PMID 27249027, 2016).
acute myeloid leukemia (2 papers, 2025). Acute myeloid leukemia (AML) is a group of neoplasms arising from precursor cells committed to the myeloid cell-line differentiation. "The CXCL5-Fc and CXCL1-Fc fusion proteins showed greater binding than the native chemokines to THP-1 cells, which are acute myeloid leukemia (AML) cells of myeloid origin and CXCR2-positive." (PMID 40427538, 2025).
alcoholic hepatitis (2 papers, 2017 to 2025). Acute hepatitis resulting from ingestion of alcohol. "The inflammatory mediator CXCL-5 is released by DR cells and is overexpressed in patients with alcoholic hepatitis." (PMID 40180915, 2025).
Allergy (2 papers, 2023 to 2025). An allergy is an immune response or reaction to substances that are usually not harmful. "Several known pathologies are associated with increased expression of CXCL5, including COPD from cigarette smoking, infections, and allergy." (PMID 37373252, 2023).
Alzheimer disease (2 papers, 2022 to 2024). A progressive, neurodegenerative disease characterized by loss of function and death of nerve cells in several areas of the brain leading to loss of cognitive function such as memory and language. "Six of the identified 33 proteins for Alzheimer’s disease in plasma samples corresponded with our findings in serum samples and can now be considered replicated by our study (Casp-8, CXCL5, CXCL6, ST1A1, TRAIL, uPA)." (PMID 36085081, 2022).
aortic aneurysm (2 papers, 2009 to 2023). A ruptured aneurysm located in the wall of the proximal portion of the descending aorta proceeding from the arch of the aorta. "We also found a significant association between CXCL5 and impaired ascending aorta flow reversal, supported by previous findings in patients with aortic aneurysm, revealing that CXCL5 was overexpressed in patients compared to controls." (PMID 37304050, 2023).
bacterial meningitis (2 papers, 2013 to 2016). Inflammation of the membranes surrounding the brain and spinal cord due to a bacterial infection. "Of the CXCL chemokines, ENA-78 (CXCL5) was found to be upregulated in patients with bacterial meningitis and exhibited neutrophil chemotactic properties together with IL-8." (PMID 23997430, 2013).
breast invasive carcinoma (2 papers, 2021 to 2024). "For the chemokine family genes, CXCL3, CXCL5, and CXCL6, gene expression was positively correlated with dendritic cell infiltration in breast invasive carcinoma-Luminal A patients." (PMID 39201290, 2024). "However, in patients with Luminal A breast invasive carcinoma, there was a negative correlation found between ESR1 and CXCL3, CXCL5, and CXCL6 gene expression; and in Her-2 patients, the same relationship was seen between ESR1 and CXCL6." (PMID 39201290, 2024).
Cerebral ischemia (2 papers, 2014 to 2024). Restriction of arterial blood supply to the brain associated with insufficient oxygenation to support the metabolic requirements of the tissue. "Ashtin B. Giambrone found a significant increase in CXCL5 in the brains of rat pups by inducing placental ischemia on day 14 of gestation concomitant with cerebral ischemia." (PMID 39206161, 2024). "CXCL-5 is significantly induced after cerebral ischemia, indicating a hypoxia-triggered inflammation in the brain." (PMID 26266921, 2014). "This suggests that CXCL5 may participate in the neuroinflammatory response that accompanies acute ischemic stroke by attracting neutrophils to sites of cerebral ischemia and thus." (PMID 39206161, 2024). "During the CI/R phase, CXCL5 recruits inflammatory cytokines at sites of cerebral ischemia and disrupts cerebral vasculature; activated cerebral vasculature can exacerbate cerebral neuronal injury by expressing CXCL13; meanwhile, XCL-1 and CCL2/MCP-1 promote neuronal apoptosis." (PMID 39206161, 2024). "CXCL5 induces an aggravated pro-inflammatory environment early in VaD, which can acutely recruit neutrophils and leukocytes at the site of damage, which in turn leads to microvascular dysfunction and disruption of the blood-brain barrier, further aggravating cerebral ischemia." (PMID 39206161, 2024). "Inhibition of CXCL5, CXCL13, XCL-1,and CCL2/MCP-1 during the cerebral ischemia/reperfusion (CI/R) phase of VaD holds promise as a therapeutic strategy to mitigate microglial activation and minimize neurological injury." (PMID 39206161, 2024).
chronic prostatitis (2 papers, 2022 to 2024). An infectious or non-infectious chronic inflammatory process that affects the prostate gland. "Early studies identified that serum CXCL5 levels were the relevant marker for men with prostate diseases, including benign prostatic hyperplasia, prostatitis, and cancer progression." (PMID 39765818, 2024). "Studies related to the prostate indicated that serum CXCL5 level is the relevant marker for men with benign prostatic hyperplasia (BPH), bacterial prostatitis, or chronic prostatitis, and a circulating marker involved in the inflammatory response." (PMID 39765818, 2024).
cognitive decline (2 papers, 2023 to 2024). "This study aimed to explore the influence of the chemokine CXCL5 on WMI and cognitive decline in chronic cerebral ischemia and the underlying mechanism." (PMID 37138312, 2023). "Moreover, IL-17 signaling had been shown to mediate white matter damage and cognitive decline in humans and rats by acting on brain endothelial cells via CXCL5." (PMID 38842661, 2024). "Currently, the role of CXCL5, especially astrocytic CXCL5, in CSVD remains unclear, and we hypothesize that astrocytic CXCL5 exacerbates WMI and cognitive decline associated with chronic cerebral ischemia." (PMID 37138312, 2023). "Moreover, deletion of microglia was found to rescue the exacerbated WMI and cognitive decline induced by astrocytic Cxcl5 overexpression." (PMID 37138312, 2023). "Here, we found that CXCL5 was up-regulated mainly in astrocytes in the CC region in a mouse model of BCAS, a widely accepted animal model of CSVD with WMI and cognitive decline." (PMID 37138312, 2023). "Our study revealed that astrocyte-derived CXCL5 aggravated WMI and cognitive decline by inhibiting microglial phagocytosis of myelin debris, suggesting a novel astrocyte-microglia circuit mediated by CXCL5-CXCR2 signaling in chronic cerebral ischemia." (PMID 37138312, 2023). "Functionally, our study revealed that astrocyte specific Cxcl5 knockout improved chronic cerebral ischemia-induced WMI and related cognitive decline, which was partly attributed to the enhanced clearance of myelin debris mediated by microglia." (PMID 37138312, 2023). "Astrocytic specific Cxcl5 overexpression aggravated WMI and cognitive decline induced by chronic cerebral ischemia, while microglia depletion counteracted this effect." (PMID 37138312, 2023). "Here, we further investigated the impact of CXCL5 on WMI and related cognitive decline and explored the potential mechanisms." (PMID 37138312, 2023). "Interestingly, astrocyte-specific deletion of Cxcl5 alleviated WMI and cognitive decline in BCAS mice." (PMID 37138312, 2023). "Moreover, astrocyte-derived CXCL5 exerted its function of aggravating WMI and cognitive decline in BCAS mice in a microglia-dependent manner." (PMID 37138312, 2023).
Cognitive impairment (2 papers, 2022 to 2023). Abnormal cognition is characterized by deficits in thinking, reasoning, or remembering. "In two small, but independent, cohort studies, we show that circulating CXCL5 can function as a cross-sectional diagnostic biomarker for white matter injury on MRI and, in a longitudinal cohort, may associate with future cognitive impairment." (PMID 36543124, 2022). "These behavior data suggested that overexpression of Cxcl5 in astrocytes exacerbate cognitive impairment of BCAS in a microglia-dependent manner." (PMID 37138312, 2023). "Taken together, astrocyte specific Cxcl5 deletion ameliorated cognitive impairment under chronic cerebral hypoperfusion." (PMID 37138312, 2023).
co‐infection (2 papers, 2023 to 2025). "MHV co‐infection in ZBP1‐deficient mice synergistically amplified Il6 and Tnf expression, whereas Il1b, Cxcl1, and Cxcl5 levels remained refractory to further elevation." (PMID 40810650, 2025).
dengue (2 papers, 2018 to 2020). "The functions of CXCL5 have been well studied in cancer and bacterial infection but rarely and ambiguous in dengue." (PMID 29651328, 2018).
diarrhoea (2 papers, 2016 to 2022). "Some of the DEGs in diarrhoea-susceptible sheep, enriched in GO terms and sub-network analysis, included IL-6, LOC101121216 (serum amyloid A), SIGLEC1, CHI3L1, S100A9, CD14, CD68, CD86, Ovar-DRB1, IL1RL1, LOC101103238 (CXCL5), CCL22 and IL1RN." (PMID 35576023, 2022).
eosinophilia (2 papers, 2015 to 2025). "Indeed, depletion of CD4+ cells just before final allergen challenge or genetic ablation of IL-17A/F compromised CXCL5 accumulation and allergic neutrophilia, but not eosinophilia, in the airways of LH mice despite their extensive inhalation experience." (PMID 39965565, 2025).
fibromyalgia (2 papers, 2020 to 2025). A chronic disorder of unknown etiology characterized by pain, stiffness, and tenderness in the muscles of neck, shoulders, back, hips, arms, and legs. "Elevated chemokines like CXCL5 and CCL20 are also observed in fibromyalgia, suggesting common immune activation mechanisms with ME/CFS." (PMID 40427027, 2025).
fungal infection (2 papers, 2015 to 2023). "Since the patient’s neutrophils did not exhibit a primary chemotaxis defect, we next measured levels of the neutrophil-targeted chemokines CXCL1, CXCL2, CXCL5 and IL-8 in the infected CSF by Luminex array at different prospective time-points during uncontrolled fungal infection." (PMID 26679537, 2015).
gastritis (2 papers, 2020 to 2025). Inflammation of the stomach. "Previous studies have suggested that increased expression of CCL20 and CXCL5 in gastritis tissue can recruit T cells and neutrophils to the gastric mucosal inflammation sites, respectively." (PMID 33426088, 2020). "This study indicated that the development of gastritis required the collaboration of CXCL5 and CCL20, recruiting not only T cells and neutrophils but also activated B cells." (PMID 33426088, 2020).
Hepatitis (2 papers, 2017 to 2019). Inflammation of the liver. "The liver transcriptional expressions of CXCL1, CXCL2, CXCL3, CXCL5, CCL2, and CCL6 significantly increased in WT and IL-33 KO mice during L2-MHV3-induced hepatitis compared to those in control PBS-injected mice as soon as 48 h PI and at 72 h PI." (PMID 28607531, 2017).
Hypercholesterolemia (2 papers, 2016 to 2022). An increased concentration of cholesterol in the blood. "Emerging evidence indicates that the plasma levels of some platelet chemokines, such as CXCL4, CCL5, CXCL5, CXCL1, CCL2 and CXCL8, are increased in hypercholesterolemia." (PMID 27933092, 2016). "In the present study, we first showed that long-term supplementation with purified anthocyanins reduced the plasma levels of the platelet chemokines CXCL7, CXCL5 and CXCL12 in subjects with hypercholesterolemia." (PMID 27933092, 2016).
infarction (2 papers, 2016 to 2017). A localised pathological necrosis of tissue resulting from obstruction of the blood supply usually by a thrombus, an embolus, or vascular torsion. "The results from the present study identify suppression of myocardial CXCL2 and CXCL5 chemoattractant expression by 11β-HSD1 as a novel mechanism with potential for regulation of neutrophil recruitment to the injured myocardium following infarction." (PMID 28522730, 2017).
injury (2 papers, 2024 to 2025). Damage inflicted on the body as the direct or indirect result of an external force, with or without disruption of structural continuity. "For example, studies have shown elevated transcript or protein levels of CXCL5, CX3 CL1, and XCL1 in neuronal cell bodies following nerve injury." (PMID 40217284, 2025).
laryngeal squamous cell carcinoma (2 papers, 2020 to 2025). A squamous cell carcinoma that arises from the larynx. "Another study reported that CXCL5 expression is significantly upregulated in laryngeal squamous cell carcinoma (LSCC), and elevated CXCL5 expression correlates strongly with increased intratumoral neutrophil infiltration." (PMID 40650111, 2025). "In laryngeal squamous cell carcinoma, neutrophils mediated by CXCL5 promoted tumor cells to escape immune surveillance by inhibiting T cell proliferation and cytokine secretion." (PMID 32201508, 2020).
leptospirosis (2 papers, 2019 to 2024). A contagious bacterial infection caused by spirochetes of the genus Leptospira. "The increased concentration of this molecule detected in our study in the serum of patients with leptospirosis is in line with our previous in vivo studies, which demonstrated that CXCL5 is inhibited in susceptible mice and increased in resistant ones, implying an importance for the host response." (PMID 39534703, 2024). "The main findings were that CCL5, CXCL5, and CXCL9 are highly expressed during leptospirosis, indicating a special role of these molecules in the immunity and pathogenesis of the disease." (PMID 39534703, 2024). "The main findings in our study were that CCL5, CXCL5, and CXCL9 are highly expressed in human leptospirosis disease." (PMID 39534703, 2024). "It has been described that CXCL5 leads to CXCL3, CXCL1, and CXCL14 expression, which are all potent chemoattractants for neutrophils, indicating the occurrence of this mechanism on leptospirosis immune response." (PMID 39534703, 2024). "In previous studies, we have shown that CCL2, CXCL5, and CCL8 are involved in the leptospirosis process, although the mechanisms are not understood." (PMID 39534703, 2024).
metabolic syndrome (2 papers, 2017 to 2024). A cluster of metabolic risk factors for CARDIOVASCULAR DISEASES and TYPE 2 DIABETES MELLITUS. "So, inhibition of CXCL5 signaling can be used as a therapeutic modality for metabolic syndrome." (PMID 29387827, 2017).
necrotizing enterocolitis (2 papers, 2016 to 2025). Necrotizing enterocolitis (NEC) is a devastating disease that affects mostly the intestine of premature infants. "Symptoms of necrotizing enterocolitis (NEC) were associated with elevated levels of IL-6, while the development of cerebral intraventricular hemorrhage in neonates correlated with high CXCL-5 (p = 0.037) and sepsis was associated with high IL-10 levels (p = 0.02)." (PMID 40244141, 2025). "In addition, elevated CXCL5 levels were observed in the gastric fluids of preterm infants at birth, who subsequently developed severe bronchopulmonary dysplasia, and in the surgically resected intestinal samples of preterm infants with necrotizing enterocolitis." (PMID 26738635, 2016).